XRCC5 (X-ray repair cross complementing 5)
Diseases named in the same sentence as XRCC5 in open-access papers (continued):
Sharing a sentence is not in itself a finding about the gene and the disease.
oral cancer (3 papers, 2013 to 2022). "Another SNP rs207943 of XRCC5 also showed significant association with oral cancer." (PMID 23437280, 2013). "As for XRCC5 (also named Ku80), there were significant differences between oral cancer and control groups in the distributions of their genotypes (P = 0.0038) and allelic frequencies (P = 0.0044) in the Ku80 promoter G-1401T (rs828907) SNP." (PMID 25705582, 2015). "The present study suggests that MSH3, XRCC5, MRE11A and PRKDC to be the four most important genes that would modify the risk of predisposition to oral cancer and leukoplakia in these eastern Indian populations." (PMID 23437280, 2013). "We performed a case-control association study to identify risk SNPs at major DSB repair (RAD50, MRE11A, NBS1, PRKDC, XRCC5, XRCC6 and LIG4), MMR (MSH6 and MSH3) and key DNA damage response (ATM and ATR) genes in oral cancer and leukoplakia patients from the state of West Bengal of eastern India." (PMID 23437280, 2013).
acute promyelocytic leukemia (2 papers, 2008 to 2021). An aggressive form of acute myeloid leukemia (AML), characterized by arrest of leukocyte differentiation at the promyelocyte stage, due to a specific chromosomal translocation t(15;17) in myeloid cells. "In patients who developed therapy-related-acute promyelocytic leukemia (t-APL) following mitoxantrone treatment of multiple sclerosis (MS), a marked linkage with 1572G > A polymorphism in XRCC5 gene has been observed." (PMID 34732266, 2021). "It is noteworthy that homozygous variants of BRCA2 and XRCC5 are associated with a greater risk of secondary acute promyelocytic leukemia (APL)." (PMID 34732266, 2021).
endometriosis (2 papers, 2018 to 2021). The growth of functional endometrial tissue in anatomic sites outside the uterine body. "Compared to endometriosis without cancer, XRCC5 was overexpressed in OCCC associated with endometriosis." (PMID 34659566, 2021). "Five novel biomarkers, eEF1A2, PTCH2, PPP1R14B, PPP2R1A, and XRCC5 are strongly overexpressed in OCCC and associated endometriosis but not in benign endometriosis." (PMID 34659566, 2021). "It was reported that OCCC-associated endometriosis already harbors aberrant gene expression, such as altered expressions of eEF1A2, PTCH2, PPP1R14B, and XRCC5, which may not be found in endometriosis tissue in the absence of cancer." (PMID 29941051, 2018).
esophagitis (2 papers, 2022 to 2024). An acute or chronic inflammatory disease affecting the esophageal wall. "Further analysis revealed a stronger association between the XRCC5 allele with severe (grade 3 or higher) esophagitis (OR=5.71 [95% CI, 1.30-25.0]; P=0.03)." (PMID 35912186, 2022). "SNPs in DNA repair-associated XRCC5 (rs3835) and XRCC1 (rs25487) were associated with an increased risk of high-grade esophagitis and pneumonitis, respectively." (PMID 38255239, 2024). "SNPs in the DNA repair-associated XRCC5 (rs3835) and XRCC1 (rs25487) were associated with an increased risk of high-grade esophagitis and pneumonitis respectively." (PMID 35912186, 2022).
HIV-1 infection (2 papers, 2013 to 2022). The type species of lentivirus and the etiologic agent of acquired immunodeficiency syndrome (AIDS). "In this study, we conducted a case-control study in the northern Han Chinese population to investigate associations of 22 SNPs in XRCC7, XRCC6, XRCC5, XRCC4, and LIG4 genes with the risk of HIV-1 infection and the progression of AIDS." (PMID 36312587, 2022). "In the process of HIV-1 infection, the XRCC5 gene is closely related to HIV-1 integration and translation." (PMID 36312587, 2022).
lymph node metastasis (2 papers, 2012 to 2023). "A risk model based on XRCC4, XRCC5 and XRCC6 showed that the risk score was related to the prognosis, gender, clinical stage, T stage, lymph node metastasis and metastasis of LUAD patients and was an independent risk factor for the prognosis of LUAD patients." (PMID 37737707, 2023).
radiation pneumonitis (2 papers, 2021 to 2022). Inflammation of the lung due to harmful effects of ionizing or non-ionizing radiation. "The XRCC5 rs3835 allele has been implicated in the development of severe radiation pneumonitis in NSCLC patients." (PMID 35912186, 2022).
Serous Ovarian Carcinoma (2 papers, 2010 to 2013).
T-cell lymphoma (2 papers, 2016 to 2024). "Similarly, inhibition of Pim kinase in T-cell lymphoma cells downregulated genes involved in DNA repair, including XRCC2 (HR), XRCC5 (encoding Ku80, in the NHEJ pathway), and ERCC8 (nucleotide excision repair)." (PMID 27374090, 2016).
AIDS (1 paper, 2022). A syndrome resulting from the acquired deficiency of cellular immunity caused by the human immunodeficiency virus (HIV). "In stratified analysis, XRCC5 rs16855458 was significantly associated with CD4+ T cell counts in AIDS patients, whereas LIG4 rs1805388 was linked to the clinical phases of AIDS patients." (PMID 36312587, 2022). "We propose that the rs16855458 in XRCC5 intron may regulate the transcription and expression of the XRCC5 by alternative splicing, which interacts with HIV-1 to promote its integration and translation, leading to the decrease in the CD4+ T lymphocyte count and the AIDS acceleration." (PMID 36312587, 2022).
astrocytomas (1 paper, 2016). "The findings of this study suggested an association surgical approach, chemotherapy, SNP in the XRCC5 gene and the risk for astrocytoma prognosis in Xi'an population." (PMID 27852033, 2016). "In conclusion, we investigated an association between XRCC3, XRCC4 and XRCC5 gene polymorphism and the risk and prognosis of astrocytoma in Chinese Han population." (PMID 27852033, 2016). "The SNP (rs9288516) in XRCC5 (HR: 1.69, 95%CI: 1.04 - 2.77, p = 0.049), surgical approach (HR: 0.61, 95%CI: 0.43 - 0.88, p = 0.003) and chemotherapy (HR: 0.71, 95%CI: 0.50 - 0.99, p = 0.029) were associated with astrocytoma prognosis." (PMID 27852033, 2016). "We have found evidence suggesting that the genotypes of XRCC5 may be correlated with increased risk and poor prognosis for astrocytoma." (PMID 27852033, 2016). "In this study, we want to explore the relationship between DNA repair genes (XRCC3, XRCC4 and XRCC5) and prognosis of astrocytoma in the Chinese Han population." (PMID 27852033, 2016). "So, we want to determine the effect of DNA repair genes (XRCC3, XRCC4 and XRCC5) on the prognosis of astrocytoma in our research." (PMID 27852033, 2016). "The results indicated that surgical approach, chemotherapy and XRCC5 gene influence the prognosis of astrocytoma patients." (PMID 27852033, 2016). "By multivariate cox regression analysis, we found that rs9288516 in XRCC5 gene influence the prognosis of astrocytoma patient." (PMID 27852033, 2016). "Although we have found that the XRCC5 gene may affect the prognosis of astrocytoma patients, there are still some problems that need to be improved in this study." (PMID 27852033, 2016). "However, the role of the XRCC5 gene in astrocytomas has not been studied." (PMID 27852033, 2016).
Burkitt lymphoma (1 paper, 2015). A rare form of malignant mature B-cell non-Hodgkin lymphoma. "In addition, direct siRNA silencing of XRCC5 also enhanced low-dose SASP (0.1mM)-induced apoptosis for Burkitt's lymphoma BL-41 cells, while targeting XRCC5 induced no apoptosis for primary human CD19+ B cells isolated from peripheral blood of healthy donor." (PMID 25860939, 2015).
chronic myelogenous leukaemia (1 paper, 2023).
chronic obstructive pulmonary disease (1 paper, 2019). A chronic and progressive lung disorder characterized by the loss of elasticity of the bronchial tree and the air sacs, destruction of the air sacs wall, thickening of the bronchial wall, and mucous accumulation in the bronchial tree. "XRCC5 is an ATP-dependent DNA helicase mapped to chromosome 2q35 and has been suggested as a potential chronic obstructive pulmonary disease susceptibility gene." (PMID 30897137, 2019).
cyst (1 paper, 2021). A sac-like closed membranous structure that may be empty or contain fluid or amorphous material. "XRCC5 and XRCC6 were also increased by 1.79-fold (95% CI (1.68, 1.90); q < 0.01) and 1.65-fold (95% CI (1.53, 1.78); q < 0.001), respectively, in ADPKD tissue, and this was maintained in all cyst sizes." (PMID 34638853, 2021).
diabetic nephropathy (1 paper, 2023). "Although, to the best of our knowledge, not much is known about a possible role of the DNA repair proteins, XRCC5 and XRCC6, in the context of diabetic nephropathy." (PMID 36769128, 2023).
granulosa cell tumour (1 paper, 2020). "As FOXL2 is highly expressed in ovarian granulosa cells and plays pivotal roles in ovarian development, the interaction of FOXL2 with XRCC5 and XRCC6 was examined in human ovarian granulosa cell tumour-derived KGN cells." (PMID 32332759, 2020).
infertile (1 paper, 2017). "In VNTR polymorphism of XRCC5 (rs6147172), among 10 probable genotypes, we observed 8 and 7 of them in control and male infertile groups, respectively." (PMID 28421111, 2017).
male infertility (1 paper, 2017). The inability of the male to effect fertilization of an ovum after a specified period of unprotected intercourse. "The results of our study showed that carriers of the 2R allele of XRCC5 VNTR were associated with a significantly decreased risk of male infertility." (PMID 28421111, 2017). "The 2R allele and 2R allele carriers of XRCC5 VNTR polymorphism significantly decreased risk of male infertility." (PMID 28421111, 2017). "Moreover, the 2R allele of XRCC5 also significantly reduced the risk of male infertility, suggesting that the presence of 2R allele in XRCC5 VNTR gene polymorphism may be a protective factor for male infertility." (PMID 28421111, 2017). "We evaluate the association between genetic polymorphisms of XRCC5 VNTR, XRCC6 -61C>G, and XRCC7 6721G>T with male infertility susceptibility." (PMID 28421111, 2017). "In conclusion, this study provided evidences that the XRCC5 VNTR, XRCC6, and XRCC7 6721G>T gene polymorphisms were associated with male infertility risk." (PMID 28421111, 2017). "Our results indicate the association of XRCC5 VNTR, XRCC6 -61C>G, and XRCC7 6721G>T gene polymorphisms with male infertility in Iranian men." (PMID 28421111, 2017). "Large cohort and diverse ethnicity studies as well as further functional analysis are needed to elucidate the biological mechanism of these polymorphisms of XRCC5, XRCC6, and XRCC7 in male infertility." (PMID 28421111, 2017). "However, our result showed significant association between XRCC5, XRCC6, and XRCC7 gene polymorphisms and male infertility in an Iranian cohort." (PMID 28421111, 2017). "Since the Ku protein, Ku70 (XRCC6)/80 (XRCC5), and DNA-PKcs (XRCC7) as critical components of NHEJ play important role in DNA integrity of spermatogenesis and can affect the offspring, we hypothesize that genetic variation of these genes may contribute to male infertility risk." (PMID 28421111, 2017).
pulmonary embolism (1 paper, 2020). The obstruction of the pulmonary artery or one of its branches by an embolus, sometimes associated with infarction of the lung. "For the cardiac G×G, one SNP pair was identified through Biofilter modeling associated with venous thrombosis or pulmonary embolism: rs7735781 in XRCC4 and rs10804247 in XRCC5 (uncorrected LRT p = 3.20×10−6 and Bonferroni-adjusted LRT p = 0.0626996)." (PMID 32915819, 2020). "One SNP-SNP model in genes XRCC4 and XRCC5 was generated by Biofilter and identified as a significant interaction for venous thrombosis and/or pulmonary embolism." (PMID 32915819, 2020).
rectal cancer (1 paper, 2016). A primary or metastatic malignant neoplasm that affects the rectum. "The only observed exception was for XRCC5 rs1051677 when comparing only rectal cancer patients with controls (codominant model: OR 3.84, 95% CI 1.11–13.31, p = 0.03; recessive model: OR 3.75, 95% CI1.08–12.95, p = 0.04)." (PMID 26735576, 2016).
retinitis pigmentosa (1 paper, 2023). Retinitis pigmentosa (RP) is an inherited retinal dystrophy leading to progressive loss of the photoreceptors and retinal pigment epithelium and resulting in blindness usually after several decades. "We found a decrease of the Xrcc5−/− central retina thickness as a consequence of a thinner ONL, which also occurs in multiple forms of retinitis pigmentosa." (PMID 36833221, 2023).
Stroke (1 paper, 2020). Sudden impairment of blood flow to a part of the brain due to occlusion or rupture of an artery to the brain. "XRCC5 is associated with the development of the thalidomide-related thrombosis as the response to the red blood cell apoptosis, which may associate to the formation of venous thrombosis and the development of CAD, PVD, stroke, and other cardiac diseases." (PMID 32915819, 2020).
thrombosis (1 paper, 2020). "Using Biofilter, one interaction nearly met Bonferroni significance: an interaction between rs7735781 in XRCC4 and rs10804247 in XRCC5 was identified for venous thrombosis with a Bonferroni-adjusted likelihood ratio test (LRT) p: 0.0627." (PMID 32915819, 2020).
tumor (83 papers, 2000 to 2025). "This study suggests that SNPs of XRCC5 are associated with the development and progression of various tumours." (PMID 37679817, 2023). "In both cases, CoREs changed from A to B subcompartments in tumours, and this repositioning was concomitant with increased H3K27me3 levels and loss of chromatin interactions with XRCC5 and KIF11 promoters." (PMID 36922594, 2023). "XRCC5 KD caused significant decreases in the number of generated polyps and the tumor burden throughout the intestine, suggesting a critical role of XRCC5 in ApcMin/+-driven CRC tumorigenesis." (PMID 35910805, 2022). "Furthermore, inhibited expression of X-ray repair cross-complementing 5 (XRCC5) in ESCC cells has been linked to reduced malignancies of tumor cells, such as proliferation, clonal progression, and apoptosis escape." (PMID 34976055, 2021). "However, relatively few studies have investigated relationships between XRCC5 polymorphisms and tumor susceptibility." (PMID 33734613, 2021). "An analysis of the relationships between GRSF1 and tumor stem cell markers revealed significant positive associations with UBE2K, XRCC5, SNRPD3, and CDC123 (Appendix B Figure A2c), which was consistent with previous findings." (PMID 40722682, 2025). "Univariate Cox analysis showed that the tumor stage, XRCC4, XRCC5, and XRCC6 were potential risk factors for the OS in patients with LUAD, while no such statistically significant genes were found in patients with LUSC (P < 0.05)." (PMID 34486486, 2021). "Functionally, XRCC5 acts as a double-edged sword by inhibiting or promoting tumor progression in different tumor types." (PMID 30217218, 2018). "In vitro, the primary biological functions of CLC-3 were suppressed after XRCC5 knockdown and promoted after XRCC5 overexpression, reconfirming the tumor-promoting action of XRCC5." (PMID 30217218, 2018). "Collectively, these results indicate that the expression and function of CLC-3 are regulated by XRCC5 in vitro and that XRCC5 is a tumor-promoting factor in GC." (PMID 30217218, 2018). "Experiments with an animal model with tumor xenografts also indicated that knockdown of XRCC5 inhibited tumor growth, and this suppression effect of XRCC5 knockdownon tumor growth was partially attenuated by LPS." (PMID 29049411, 2017). "So the function of XRCC5 is a double-edged sword, XRCC5 isalso a tumor promoting factor in tumor cells." (PMID 29049411, 2017). "As instability of genome and chromosomes play key roles in carcinogenesis, XRCC5 is deemed to be an anti-tumor protein." (PMID 29049411, 2017). "Further tumor tissue immunohistochemistry and Western blot showed that knockdown of XRCC5 decreased XRCC5 expression, and also suppressed COX-2 expression." (PMID 29049411, 2017). "Further, the “A/A” genotype of rs9288516 in XRCC5 (HR: 1.67, 95%CI: 1.02 - 2.72, p = 0.042) had significantly outcomes after adjusting for potential confounders, patients with poor tumor differentiation and the coexistence of the unfavorable genotypes." (PMID 27852033, 2016). "Next we examined subcompartment repositioning involving the tumour suppressors XRCC5 and KIF11." (PMID 36922594, 2023). "In addition, the physical interaction between endogenous FOXL2 and XRCC5 was also observed in various non-tumour cell lines." (PMID 32332759, 2020). "In addition, the expression of CLC-3 and XRCC5 in tumor tissues presented the same variation trend as tumor growth." (PMID 30217218, 2018). "The survival analysis indicated that high expression of XRCC5 predicted poor prognosis in GC patients, prompting that XRCC5 might be a tumor-promoting factor in GC development." (PMID 30217218, 2018). "Our observations revealed that tumor growth was inhibited after XRCC5 knockdown or CLC-3 knockdown." (PMID 30217218, 2018). "Conversely, overexpression of XRCC5 promoted tumor growth and the promotion effect could be reversed by CLC-3 knockdown." (PMID 30217218, 2018).